SPTLC1 (serine palmitoyltransferase long chain base subunit 1)
Diseases named in the same sentence as SPTLC1 in open-access papers (continued):
Sharing a sentence is not in itself a finding about the gene and the disease.
hearing loss (1 paper, 2022). "Potential causative variants were identified in genes associated with nonsyndromic hearing loss (CIB2, COL11A1, ILDR1, MYO15A, TMPRSS3, and WFS1), nonsyndromic hearing loss or Usher syndrome (CDH23, MYO7A, PCDH15, and USH2A), and other syndromic forms of hearing loss (CHD7, OPA1, and SPTLC1)." (PMID 34837038, 2022).
Insulin resistance (1 paper, 2021). Increased resistance towards insulin, that is, diminished effectiveness of insulin in reducing blood glucose levels. "However, most important in the pathogenesis of insulin resistance is the de novo pathway, which begins in the endoplasmic reticulum by the action of the enzyme serine palmitoyltransferase 1 and 2 (SPTLC1 and SPTLC 2), producing 3-ketosphinganine from serine and palmitoyl-CoA." (PMID 34204938, 2021).
liver cancer (1 paper, 2024). An epithelial or non-epithelial malignant neoplasm that arises from the liver. "After analyzing six tumor-specific signatures (IDI1, GMPPA, NME1, PSMB3, SPTLC1 and EBP), the gene effect and gene dependency were measured in different non-cancerous cell lines and liver cancer lines of human HCC." (PMID 38927057, 2024).
osteosarcoma (1 paper, 2022). A usually aggressive malignant bone-forming mesenchymal neoplasm, predominantly affecting adolescents and young adults. "The results showed that CD151 and SPTLC1 expression levels were highly correlated in osteosarcoma samples." (PMID 36209197, 2022). "Next, we investigated whether CD151 mediates sphingolipid metabolism by SPTLC1 in osteosarcoma cells." (PMID 36209197, 2022). "It was speculated that CD151 might interact with c-myc pathways and regulate sphingolipid metabolism key enzyme SPTLC1 expression in osteosarcoma cells." (PMID 36209197, 2022). "Western blot analysis was used to examine the expression of SPTLC1 in osteosarcoma cells, and the results showed that the knockout of CD151 remarkably decreased, whereas CD151 overexpression significantly increased SPTLC1 protein levels." (PMID 36209197, 2022). "We found that SPTLC1 promoter activities from WT were greatly increased, whereas no obvious changes were detected from MUT in osteosarcoma cells overexpressing c-myc compared to the empty vector, respectively." (PMID 36209197, 2022).
Stroke (1 paper, 2021). Sudden impairment of blood flow to a part of the brain due to occlusion or rupture of an artery to the brain. "To investigate any possible association between the de novo sphingolipid pathways and stroke, we assessed protein expression profiles of SPTLC1 and 2, two subunits of SPT, the rate-limiting enzymes in the de novo biosynthesis of sphingolipids, in both cerebral and renal tissues." (PMID 33917593, 2021).
type 1 diabetes (1 paper, 2025). "The replicated signals targeted proteins which can be biologically linked to type 1 diabetes, such as the Serine Palmitoyltransferase Long Chain Base Subunit 1 (SPTLC1), a protein involved in the sphingolipid metabolism." (PMID 40263317, 2025).
peripheral neuropathy (11 papers, 2010 to 2025). A disorder affecting the peripheral nervous system. "In this case series, we report that the V144D mutation in SPTLC1 gene may relate to both painful and painless peripheral neuropathies." (PMID 30420926, 2018).
tumor (5 papers, 2017 to 2024). "In GBC tissues, elevated expression of SPTLC1 and CERS2, and that of their product C24-ceramide, was associated with tumor stage, distal metastasis, and poor prognosis." (PMID 34439378, 2021).
cancer (4 papers, 2018 to 2025). A tumor composed of atypical neoplastic, often pleomorphic cells that invade other tissues. "Myriocin, a competitive inhibitor of serine palmitoyltransferase 1 (SPTLC1), the first enzyme in de novo sphingolipid biosynthesis, can inhibit the proliferation of different cancer types by altering the sphingolipid rheostat." (PMID 39723240, 2024).
infection (4 papers, 2022 to 2025). The state of being infected such as from the introduction of a foreign agent such as serum, vaccine, antigenic substance or organism. "Interestingly, in the cell lines depleted for SPTLC1 or deficient for KDSR, a slightly increased number of inclusions was detected after infection with CTL2-cpoS::cat." (PMID 40794560, 2025).
neurodegenerative disease (2 papers, 2023 to 2024). A disorder of the central nervous system characterized by gradual and progressive loss of neural tissue and neurologic function. "Human SPT is a membrane-bound large protein complex containing SPTLC1/SPTLC2 heterodimer as the core subunits, and it is known that mutations of the SPTLC1/SPTLC2 genes increase the formation of deoxy-type of LCBs derived from l-Ala and Gly to cause some neurodegenerative diseases." (PMID 37030501, 2023).
retinopathy (1 paper, 2022). "In addition, Sptlc1 ECKO mice had reduced retinal neovascularization in the oxygen-induced retinopathy model." (PMID 36197001, 2022). "Sptlc1 ECKO mice exhibited delayed retinal vascular development and reduced pathological angiogenesis in an oxygen-induced retinopathy model." (PMID 36197001, 2022).
SPTLC1 also shares sentences with these, for which no sentence is quoted: macular telangiectasia type 2 (4 papers); COVID-19 (3); juvenile amyotrophic lateral sclerosis (3); and autonomic neuropathy (2); dementia (2); neurological disorder (2); Vocal cord paralysis (2); 3-methylglutaconic aciduria (1); autoimmune disease (1); Autosomal recessive spastic paraplegia type 56 (1); axonal neuropathy (1); breast carcinoma (1); Charcot-Marie-Tooth neuropathy (1); diabetic neuropathy (1); dysautonomia (1); epilepsy (1); erythromelalgia (1); Glucose intolerance (1); hereditary motor and sensory neuropathy (1); inflammatory bowel disease (1); lipodystrophy (1); lymphoma (1); metabolic syndrome (1); motor neuron degeneration (1); noise induced hearing loss (1); pancreatic disease (1); renal cell carcinoma (1); respiratory failure (1); retinal degeneration (1); schizophrenia (1).
A further 5 diseases each share a sentence with SPTLC1 in 1 paper.